CIMIP1 (ciliary microtubule inner protein 1)
Synonyms: C20orf85; LLC1; bA196N14.1
Tractability: No criterion of Open Targets' tractability assessment is met for any kind of drug.
Gene: Protein-coding gene on chromosome 20 (58,150,902 to 58,161,150, forward strand). Ensembl gene ENSG00000124237.
Subcellular location: Cell projection, cilium
Subcellular location (Human Protein Atlas): Mid piece
Gene Ontology:
Molecular function: protein binding
Cellular component: cilium
Genetic constraint (gnomAD): Loss-of-function variants: 14 observed, 16.49 expected, observed/expected ratio (o/e) 0.85, 90% interval 0.56 to 1.33. The upper end of that interval is the gene's LOEUF score, 1.33, which puts it in group 5 of 6, group 1 being the genes least tolerant of losing a copy. Missense variants: 179 observed, 170.83 expected, observed/expected ratio (o/e) 1.05, 90% interval 0.93 to 1.19. Synonymous variants: 72 observed, 66.85 expected, observed/expected ratio (o/e) 1.08, 90% interval 0.89 to 1.31.
Homologues: Orthologues: macaque CIMIP1 (97% identical), chimpanzee CIMIP1 (91% identical), dog CIMIP1 (83% identical), guinea pig CIMIP1 (79% identical), pig CIMIP1 (74% identical), rat Cimip1 (72% identical), mouse Cimip1 (71% identical), tropical clawed frog cimip1 (45% identical). Paralogues in human: CIMIP5 (22% identical).
Diseases named in the same sentence as CIMIP1 in open-access papers:
CIMIP1 is named in the same sentence as 6 diseases in open-access papers, as found by Europe PMC text mining. Sharing a sentence is not in itself a finding about the gene and the disease.
CIMIP1 shares sentences with these, for which no sentence is quoted: lung carcinoma (2 papers); tumor (2); adolescent idiopathic scoliosis (1); Alzheimer disease (1); breast carcinoma (1); cancer (1).